TNF (tumor necrosis factor)
Diseases named in the same sentence as TNF in open-access papers (continued):
Sharing a sentence is not in itself a finding about the gene and the disease.
rheumatoid arthritis (continued). "Analyses of the SNPs -174 G/C of the IL-6 gene and -308 G/A of the TNFα gene have been described as important factors capable of influencing the pathogenesis of rheumatoid arthritis (RA)." (PMID 41472214, 2025). "In patients with rheumatoid arthritis, the inflammatory response triggers the excessive secretion of cytokines, such as tumor necrosis factor-alpha (TNF-α) and interleukin-6 (IL-6)." (PMID 40538801, 2025). "SII also plays a significant role in evaluating the clinical efficacy of TNF-α inhibitors in patients with rheumatoid arthritis." (PMID 41426564, 2025). "IL-32γ is thought to be more proinflammatory, inducing TNFα and IL-6 in rheumatoid arthritis synovial fibroblasts whilst the IL-32β isoform is thought to reduce inflammation." (PMID 40977709, 2025). "Classical Monocytes from rheumatoid arthritis patients responded to TNF less prominently compared with Classical Monocytes from healthy donors." (PMID 40453083, 2025). "Another study found reduced Dickkopf-1 levels in rheumatoid arthritis patients after anti-TNF α therapy." (PMID 40762009, 2025). "By inhibiting the release of pro-inflammatory cytokines, such as TNF-α and IL-6, it emerges as a promising therapeutic agent for chronic inflammatory disorders, including rheumatoid arthritis and inflammatory bowel disease." (PMID 40076409, 2025). "Substantial convergence occurred through TNF-α research, which contributed 283 occurrences to the psoriasis theme and 294 occurrences to the rheumatoid arthritis theme." (PMID 41011289, 2025). "In rheumatoid arthritis, synoviocytes and macrophages maintain a chronic pro-inflammatory profile, sustained by IL-6 and TNF-α, inhibiting repair and promoting joint destruction." (PMID 41373540, 2025). "For instance, TNF inhibitors have been successfully used in treating rheumatoid arthritis and other inflammatory diseases, suggesting their potential for mitigating the inflammatory response in SAKI." (PMID 40166075, 2025). "Monoclonal antibodies against IL-1β (e.g., canakinumab) or TNF-α (e.g., infliximab, etanercept), already in clinical use for rheumatoid arthritis and other inflammatory diseases, hold theoretical potential for controlling periodontal inflammation." (PMID 41155385, 2025). "Elevated levels of IL-6, IL-18, IFNγ, IL-17, IL-23, and TNFα have been found in the serum of patients with rheumatoid arthritis, as well as psoriatic arthritis." (PMID 40170117, 2025). "Myostatin induces pro-inflammatory cytokines, such as TNF-α and IL-1β, in rheumatoid arthritis synovial fibroblasts through distinct signaling pathways." (PMID 40427596, 2025). "It has been demonstrated that TNF, a pro‐inflammatory factor, and anti‐TNF antibodies or Fc fusion proteins (TNF blockers) have shown remarkable efficacy in autoimmune‐related diseases such as rheumatoid arthritis and Crohn's disease." (PMID 40165483, 2025). "Diseases that lead to chronic production of IL-1β and TNF-a, such as autoinflammatory syndromes and rheumatoid arthritis, can be a target for Resv, especially considering that the incidence of these conditions increases with age." (PMID 40076963, 2025). "Conversely, in rheumatoid arthritis, macrophages exacerbate inflammation and tissue damage by releasing pro-inflammatory cytokines such as IL-6 and TNF-α." (PMID 40055311, 2025). "Adalimumab, a fully humanized anti-TNF-alpha agent, was initially approved for the treatment of psoriasis and rheumatoid arthritis." (PMID 40872580, 2025). "Many chronic inflammatory and autoimmune disorders, including psoriasis, ankylosing spondylitis, inflammatory bowel disease, and rheumatoid arthritis, are characterized by abnormal or excessive TNF production." (PMID 41304898, 2025). "TNF-α also plays a key role in autoimmune diseases, such as rheumatoid arthritis, inflammatory bowel disease, and psoriasis, where its aberrant activity contributes to chronic inflammation and tissue damage." (PMID 40430212, 2025).
rheumatoid arthritis (continued). "While anti-TNF biologics have proven successful in treating conditions like psoriasis and rheumatoid arthritis, they face significant limitations including immunogenicity, adverse effects, and high costs." (PMID 40807350, 2025). "Clinical trials explored the therapeutic value of monoclonal anti-TNF-α treatments, with some documenting significant relief of pain in rheumatoid arthritis, ankylosing spondylitis, and chronic radiculopathy." (PMID 40430212, 2025). "The reduction in pro-inflammatory cytokines, particularly TNF-α and IL-6, aligns with the known role of these mediators in driving synovial inflammation and joint destruction in rheumatoid arthritis." (PMID 40332334, 2025). "Inflammatory bone disorders, such as rheumatoid arthritis and periodontitis, are often characterized by TNF-α-driven excessive osteoclast formation, which contributes to pathological bone loss." (PMID 41516077, 2025). "Patients with rheumatoid arthritis who use TNF-α inhibitors are more likely to get significant infections than those with psoriatic arthritis or ankylosing spondylitis." (PMID 40371340, 2025). "The intersection genes of signaling pathways such as NF‐kappa B, TNF, macrophage differentiation, rheumatoid arthritis and Ras are also considered to be closely related to the osteoclast differentiation function." (PMID 40051055, 2025). "Prolonged production of TNF‐α in individuals diagnosed with rheumatoid arthritis can lead to tissue inflammation and damage, ultimately resulting in bone and cartilage degradation." (PMID 41049417, 2025). "HLA testing before initiating anti-TNF therapy opens the door to a personalized approach to the treatment of inflammatory diseases such as rheumatoid arthritis, Crohn’s disease, and psoriasis." (PMID 40806407, 2025). "Targeting cytokines such as TNF-α and IL-6 has been effective in reducing inflammation in autoimmune disorders like rheumatoid arthritis." (PMID 40364844, 2025). "Adalimumab was an anti-tumor necrosis factor (TNF) drug used to treat inflammatory joint conditions such as rheumatoid arthritis." (PMID 41291434, 2025). "Rheumatoid arthritis patients are characterized by elevated levels of pro-inflammatory cytokines such as TNF-α, IL-6, IL-1β, and CRP, which reflect heightened inflammatory activity." (PMID 40709173, 2025). "Our study also showed that in all five treatment groups, patients with rheumatoid arthritis exhibited higher levels of TNF‐α compared to healthy individuals, underscoring the significance of this cytokine in the pathogenesis of rheumatoid arthritis." (PMID 40099178, 2025). "Although the mechanism of TNF-α has been extensively studied, TNF-α inhibitors are widely used in treating psoriasis, rheumatoid arthritis, and other immune-related diseases." (PMID 40226618, 2025). "The next approved drug in Japan is Ozoralizumab, which is used in rheumatoid arthritis targeting tumor necrosis factor-alpha." (PMID 41009364, 2025). "The severity of rheumatoid arthritis is directly correlated with serum and synovial TNF‐α levels, and numerous drugs targeting this cytokine have been developed for the treatment of the disease." (PMID 40099178, 2025). "The Oral Rheumatoid Arthritis Trial (ORAL) Surveillance, a landmark post-marketing safety study, revealed an association between tofacitinib and a higher risk of MACE compared to anti-TNF-α agents in patients with RA aged ≥50 years with cardiovascular risk factors, thereby raising concerns." (PMID 40526615, 2025). "It is worth noting that patients with rheumatoid arthritis are more likely to develop infections undergoing treatment with TNF-α inhibitors." (PMID 40371340, 2025). "KEGG analysis revealed significant enrichment in pathways such as rheumatoid arthritis, cytokine–cytokine receptor interactions, tumor necrosis factor signaling, and NF-kappa B signaling." (PMID 40427104, 2025).
rheumatoid arthritis (continued). "TNF-α is a multifunctional cytokine, reported to be present in various chronic inflammatory, autoimmune, and viral diseases, such as rheumatoid arthritis, systemic lupus erythematosus, diabetes, and SARS-CoV-2." (PMID 40872208, 2025). "The downregulation of TNF-α has become a cornerstone in treating various inflammatory and autoimmune disorders, including psoriasis, rheumatoid arthritis, and ankylosing spondylitis." (PMID 40004039, 2025). "It significantly reduced the expression of IL-1, IL-6, IL-17, and TNF-α in rats with rheumatoid arthritis (p < 0.05)." (PMID 40006536, 2025). "The second case had severe cerebral toxoplasmosis along with low level EBV viremia in a patient with rheumatoid arthritis on anti-TNF alpha therapy (among other regimens)." (PMID 41156612, 2025). "KEGG analysis showed that the top five enriched pathways were ‘Viral protein interaction with cytokine and cytokine receptor’, ‘Rheumatoid arthritis’, ‘IL‐17 signalling pathway’, ‘Cytokine‐cytokine receptor interaction’ and ‘TNF signalling pathway’." (PMID 41013715, 2025). "Tumor necrosis factor inhibitors (TNFi) have significantly improved the management of rheumatoid arthritis (RA), offering relief from joint inflammation and the associated risk of cartilage and bone damage." (PMID 40415615, 2025). "Recent studies have explored the potential of mitigating rheumatoid arthritis by inhibiting tumor necrosis factor-induced caspase-3 activity." (PMID 40141133, 2025). "MAbs, such as Infliximab and Adalimumab, which directly neutralize TNF-α, are extensively utilized in the treatment of autoimmune disorders, including inflammatory bowel disease and rheumatoid arthritis." (PMID 40507795, 2025). "The top three pathways enriched in downregulated DEGs are the TNF signaling pathway, rheumatoid arthritis, and cytokine-cytokine receptor interaction." (PMID 40918457, 2025). "The sustained inhibitory effects of PTD on key inflammatory markers (NO, TNF-α, and IL-6) underscore its therapeutic potential in managing chronic inflammatory conditions like rheumatoid arthritis." (PMID 40332334, 2025). "In fact, targeted treatment against TNF-α has been initiated in various autoimmune diseases, such as TNF-α inhibitors significantly improving clinical symptoms in inflammatory bowel disease, rheumatoid arthritis, and psoriasis." (PMID 40418396, 2025). "In patients with rheumatoid arthritis (RA) taking anti-TNF drugs, it is utterly unique to report a case of isolated NTB without other systemic manifestations." (PMID 40851998, 2025). "Anti-TNF-α treatments, such as infliximab and adalimumab, have shown benefits in systemic inflammatory illnesses such as rheumatoid arthritis and Crohn’s disease." (PMID 39861166, 2025). "Anti-cytokine therapies targeting Tumor Necrosis Factor Alpha have greatly succeeded in treating rheumatoid arthritis in many patients." (PMID 40453083, 2025). "TNF inhibitors revolutionized the treatment of multiple autoimmune conditions such as Crohn’s disease, rheumatoid arthritis, psoriasis, psoriatic arthritis, ankylosing spondylitis, and juvenile idiopathic arthritis." (PMID 40725812, 2025). "Adalimumab is a widely used biologic anti-TNF-α-agent for moderate to severe hidradenitis suppurativa and many other autoimmune diseases, including rheumatoid arthritis, ankylosing spondylitis, Crohn’s disease, and uveitis of the posterior segment." (PMID 41142785, 2025). "This interaction enables the expansion of Tregs, which in turn suppress the differentiation of the CD8+ T cells in rheumatoid arthritis (RA) patients responding to anti‐TNF therapy." (PMID 40977146, 2025). "In another study, the daily oral administration of sesamin for 6 weeks improved the number of tender joints in patients with rheumatoid arthritis through reductions in serum levels of C reactive protein, TNF-α, and cyclooxygenase-2." (PMID 40142993, 2025).
rheumatoid arthritis (continued). "These TNF-α inhibitors have been effective in managing rheumatoid arthritis (RA) by reducing disease activity, slowing joint damage, and preserving function." (PMID 40142915, 2025). "Increased glucose uptake in rheumatoid arthritis fibroblasts after tumor necrosis factor stimulation." (PMID 41036386, 2025). "Adalimumab is a recombinant human IgG1 mAb targeting tumor necrosis factor-alpha (TNF-α) that has transformed the treatment of autoimmune diseases such as rheumatoid arthritis and Crohn’s disease." (PMID 40922426, 2025). "Tumor necrosis factor α (TNF-α) is a centraldriverof inflammation in autoimmune conditions such as Crohn’s diseaseand rheumatoid arthritis (RA)." (PMID 40575322, 2025). "ADAM17 cleaves TNF and IL-6 receptor and is a central drug target for inflammatory conditions, such as sepsis and rheumatoid arthritis." (PMID 40081988, 2025). "Particularly encouraging are results demonstrating sustained efficacy of anti-tumor necrosis factor humanized VHH in the treatment of rheumatoid arthritis." (PMID 41011175, 2025). "In contrast, TNFα blockers have been essential in managing rheumatoid arthritis and Crohn’s disease by inhibiting proinflammatory cytokines, later expanding to conditions like psoriatic arthritis." (PMID 40557148, 2025). "The overproduction of pro‐inflammatory cytokines TNF‐α, IL‐1β, and IL‐6 was observed in concanavalin A‐activated peripheral blood mononuclear cells and macrophages extracted from patients with rheumatoid arthritis induced by ENO1." (PMID 40586619, 2025). "Antibodies against TNFα, like eternacept, infliximab and adalimumab, were designed to treat rheumatoid arthritis, ulcerative colitis and Crohn’s disease." (PMID 40722873, 2025). "Propolis effectively modulates inflammatory pathways, including NF-κB, reducing cytokines such as TNF-α and IL-6, thus demonstrating efficacy in managing chronic inflammatory conditions like atherosclerosis and rheumatoid arthritis." (PMID 40906303, 2025). "Adalimumab, a fully human monoclonal antibody targeting tumor necrosis factor-alpha (TNF-α), is widely used in the treatment of autoimmune diseases such as rheumatoid arthritis, Crohn’s disease, and psoriasis." (PMID 40860891, 2025). "Adalimumab blocks tumor necrosis factor-alpha (TNF-α), and it is used, among others, in rheumatoid arthritis, psoriatic arthritis, or Crohn’s disease." (PMID 41009364, 2025). "Patients with rheumatoid arthritis who developed paradoxical psoriasis under TNF-α inhibitor therapy showed an increase in Th17 cells and IL-17A production." (PMID 41142785, 2025). "As an example, the binding of PlGF to Flt-1 in patients with rheumatoid arthritis stimulated the production of proinflammatory cytokines, including TNF-α and IL-6 in monocytes, enhancing inflammation." (PMID 40800007, 2025). "This system is designed to co-deliver hydroxychloroquine and TNF-α-targeting siRNA to treat rheumatoid arthritis." (PMID 39861693, 2025). "Adalimumab, a TNFα inhibitor, is similarly under investigation for autoimmune conditions such as rheumatoid arthritis (NCT03938701) and Crohn’s disease (NCT01564823)." (PMID 40557148, 2025). "We propose a TNF‐hypersecreting phenotype described in rheumatoid arthritis patients also has a role in the inflammatory response differences observed between rural and urban populations living in Africa." (PMID 40489164, 2025). "Numerous studies have shown low HDL-C but high TG in inflammatory and autoimmune diseases, including sepsis, IBD, systemic lupus erythematosus, and rheumatoid arthritis, and cytokines like TNFα, IL-1β, and IL-6 are thought to be involved." (PMID 40484317, 2025). "RA FLS (MH7A), which is activated by TNF-α stimulation, is a widely used in vitro model of rheumatoid arthritis (RA) for investigating the specific mechanisms of potential therapeutic agents for the condition." (PMID 40732305, 2025).
rheumatoid arthritis (continued). "In rheumatoid arthritis (RA), key molecular mechanisms include the activation of proinflammatory cytokines such as TNF-α and IL-6, which drive inflammation and joint damage." (PMID 40755762, 2025). "Among these, IL-1β, IL-6, and TNF-α play a substantive role in both rheumatoid arthritis and osteoarthritis." (PMID 40491903, 2025). "Tumor Necrosis Factor Alpha is a known pro-inflammatory cytokine that plays a key role in the pathogenesis of rheumatoid arthritis." (PMID 40453083, 2025). "In this study, we investigated the serum concentrations of TNF inhibitors (TNFis) in rheumatoid arthritis (RA) patients with a well-controlled disease who gradually tapered their medication to complete cessation." (PMID 41155623, 2025). "In this study, we incubated PBMCs from healthy donors and rheumatoid arthritis patients with Tumor Necrosis Factor Alpha and then performed their single-cell multi-omics analysis via BD Rhapsody." (PMID 40453083, 2025). "Rheumatoid arthritis (RA): The increased levels of IL-1β, TNFα, and IL-6 which are found in RA also resemble a Trained Immunity phenotype." (PMID 41432375, 2025). "In this study, we performed a multi-omics analysis of the response to TNF by peripheral blood mononuclear cells of healthy donors and rheumatoid arthritis patients." (PMID 40453083, 2025). "These are accepted for thetreatment of psoriatic arthritis, ulcerative colitis, rheumatoid arthritis, andankylosing spondylitis, golimumab is a completely humanized anti-TNF monoclonalantibody." (PMID 40160593, 2025). "Rheumatoid arthritis therapy focuses on targeting the immune system’s signaling molecules, such as tumor necrosis factor (TNF) and interleukin 6 (IL-6), which are involved in the progression of the disease." (PMID 40565171, 2025). "On the other hand, there is strong evidence that TNF-α inhibitor therapy reduces the incidence of cardiovascular events in patients with inflammatory diseases such as rheumatoid arthritis." (PMID 40009347, 2025). "■Inhibition of CD4+ and CD8+ T cell proliferation and IFN-γ, TNF-α, IL-6, and IL-17 release in rheumatoid arthritis;■Reduced iNOS expression induced by LPS in murine macrophages." (PMID 40298549, 2025). "The TNF-α signaling pathway is also well documented in the pathogenesis of rheumatoid arthritis (RA), particularly in its contribution to synovial inflammation, cartilage destruction, and bone erosion." (PMID 40277922, 2025). "TNF-α is a pro-inflammatory cytokine involved in several inflammatory diseases, notably rheumatoid arthritis, asthma, cancer, and neurodegenerative diseases such as Alzheimer’s disease." (PMID 40338229, 2025). "Octreotide (OCT)—which is a first-generation SSA—modulates cytokine production in rheumatoid arthritis synoviocytes through interleukin-15 and TNF-α inhibition and increases interleukin-10 levels." (PMID 40732232, 2025). "Osteoclast formation mediated by TNF-α contributes to osteoporosis in inflammatory bone disorders, including rheumatoid arthritis and periodontal disease." (PMID 41516077, 2025). "The Ke0 parameter for PTD suggests a moderate delay in modulating TNF-α, implicating TNF-α as a primary target for PTD’s anti-rheumatoid arthritis effects in vivo." (PMID 40332334, 2025). "KEGG analysis revealed that genes in the blue module were significantly associated with pathways related to Rheumatoid arthritis, AGE-RAGE signaling in diabetic complications, Influenza A, Measles, and TNF signaling." (PMID 40996982, 2025). "The alcohol extract of FC down-regulated IL-6 and TNF-α in rheumatoid arthritis and osteoarthritis rat models and inhibited ear edema induced by xylene." (PMID 41515139, 2025). "Anti-TNFα therapy has long been carried out in the clinical treatment of autoimmune diseases such as Crohn’s disease and rheumatoid arthritis." (PMID 39856555, 2025).